KCTD6 (potassium channel tetramerization domain containing 6)
Description:
Probable substrate-specific adapter of a BCR (BTB-CUL3-RBX1) E3 ubiquitin-protein ligase complex mediating the ubiquitination and subsequent proteasomal degradation of target proteins. Promotes the ubiquitination of HDAC1; the function seems to depend on KCTD11:KCTD6 oligomerization. Can function as antagonist of the Hedgehog pathway by affecting the nuclear transfer of transcription factor GLI1; the function probably occurs via HDAC1 down-regulation, keeping GLI1 acetylated and inactive. Inhibits cell growth and tumorigenicity of medulloblastoma (MDB). Involved in regulating protein levels of ANK1 isoform Mu17 probably implicating CUL3-dependent proteasomal degradation.
Synonyms: MGC27385; KCASH3
Tractability: No criterion of Open Targets' tractability assessment is met for any kind of drug.
Gene: Protein-coding gene on chromosome 3 (58,491,078 to 58,502,360, forward strand). Ensembl gene ENSG00000168301.
Subcellular location: Cytoplasm, myofibril, sarcomere, M line
Subcellular location (Human Protein Atlas): Mitochondria; Nucleoli
Pathways (Reactome):
Gene expression (Transcription): RUNX1 regulates estrogen receptor mediated transcription
Immune System: Antigen processing: Ubiquitination & Proteasome degradation
Metabolism of proteins: Neddylation
Signal Transduction: Estrogen-dependent gene expression
Gene Ontology:
Molecular function: ankyrin binding; cullin family protein binding; identical protein binding; protein binding
Biological process: negative regulation of smoothened signaling pathway; ubiquitin-dependent protein catabolic process; protein homooligomerization; protein ubiquitination
Cellular component: cytosol; M band
Genetic constraint (gnomAD): Loss-of-function variants: 6 observed, 15.21 expected, observed/expected ratio (o/e) 0.39, 90% interval 0.22 to 0.78. The upper end of that interval is the gene's LOEUF score, 0.78, which puts it in group 3 of 6, group 1 being the genes least tolerant of losing a copy. Missense variants: 147 observed, 278.02 expected, observed/expected ratio (o/e) 0.53, 90% interval 0.46 to 0.61. Synonymous variants: 81 observed, 104.55 expected, observed/expected ratio (o/e) 0.77, 90% interval 0.65 to 0.93.
Homologues: Orthologues: chimpanzee KCTD6 (100% identical), dog KCTD6 (100% identical), macaque KCTD6 (100% identical), pig KCTD6 (100% identical), mouse Kctd6 (99% identical), rabbit KCTD6 (99% identical), guinea pig KCTD6 (97% identical), rat Kctd6 (97% identical), tropical clawed frog pxk (95% identical), zebrafish kctd6b (90% identical), zebrafish kctd6a (87% identical), Drosophila melanogaster twz (27% identical), and 1 more. Paralogues in human: KCTD21 (37% identical), KCTD11 (32% identical), KCTD15 (29% identical), KCTD7 (29% identical), KCTD1 (28% identical), KCTD4 (26% identical), KCTD8 (25% identical), KCTD12 (24% identical), KCTD18 (24% identical), KCNRG (23% identical), KCTD16 (23% identical), KCTD19 (23% identical), and 1 more.
Diseases named in the same sentence as KCTD6 in open-access papers:
KCTD6 is named in the same sentence as 6 diseases in open-access papers, as found by Europe PMC text mining. Sharing a sentence is not in itself a finding about the gene and the disease. The quoted sentences say what the papers report.
head and neck squamous cell carcinoma (1 paper, 2023). A squamous cell carcinoma that arises from any of the following anatomic sites: lip and oral cavity, nasal cavity, paranasal sinuses, pharynx, larynx, and salivary glands. "In head and neck squamous cell carcinomas (HNSCCs), the expression of the long non-coding RNA (lncRNA) lnc-LCE5A-1 and lnc-KCTD6-3 was associated with reduced overall survival, while the ectopic expression of this lncRNA decreased Vimentin mRNA levels and impaired HNSCC cell migration in vitro." (PMID 38067168, 2023).
cancer (3 papers, 2021 to 2023). A tumor composed of atypical neoplastic, often pleomorphic cells that invade other tissues. "There are currently few investigations on the correlation between KCTD6 and cancer." (PMID 36814910, 2023).
KCTD6 also shares sentences with these, for which no sentence is quoted: medulloblastoma (2 papers); atopic dermatitis (1); dyslipidemia (1); tumor (1).